PML (PML nuclear body scaffold)
Diseases named in the same sentence as PML in open-access papers (continued):
Sharing a sentence is not in itself a finding about the gene and the disease.
Obesity (9 papers, 2012 to 2024). Accumulation of substantial excess body fat. "This knowledge offers new therapeutic opportunities for targeting PTP1B, IL6 or PML-loss induced SREBP signalling in the context of obesity." (PMID 38969865, 2024). "Nevertheless, given that PML deficiency resulted in altered metabolism from a glycogenotic state to enhanced adipogenesis and even obesity in HBsAg-transgenic mice, PML could be the long-sought link between chronic HBV-infection and metabolic reprogramming toward HCC development." (PMID 27058621, 2016). "Given prior evidence on the impact of obesity on PML-RAR AMLs19, we expanded our investigation on the APL model." (PMID 38280853, 2024). "Our results also emphasize the role of PML in diet-induced obesity and cellular metabolism, and its regulation by phosphorylation." (PMID 35406736, 2022). "In contrast, PML KO mice had tissue-specific enhancement of both fatty acid β-oxidation and synthesis, increased metabolic rate, and resistance to diet-induced obesity." (PMID 32461215, 2020). "The rearrangement of glucose and fatty acid metabolic gene expression in PML knockout mice, reportedly resulted in an increased metabolic rate and counteracted Western diet-induced obesity symptoms." (PMID 33324553, 2020). "Although the role of PML as a tumor suppressor protein is well known, its role in cellular metabolism, notably under obesity or HFD conditions, is unknown or inconclusive." (PMID 35406736, 2022). "Interestingly, PML appears to be involved in several metabolism-related diseases and cardiovascular diseases such as Diabetes mellitus, Obesity, Atherosclerosis and Hypertension." (PMID 22947142, 2012). "Based on these observations, our study revealed that PML-RARα interacts with PPARγ to disrupt the PPARγ/RXR heterodimer and promote PPARγ ubiquitination and degradation, which may partially explain the obesity and dyslipidemia in newly diagnosed patients with APL that is driven by PML-RARα." (PMID 32929351, 2020).
B-cell lymphomas (8 papers, 2012 to 2025). "B-cell lymphomas deficient for E6AP expressed elevated levels of PML and PML-NBs with a concomitant increase in markers of cellular senescence, while PML deficiency accelerated the rate of Myc-induced B-cell lymphomagenesis." (PMID 38397043, 2024). "Taken together, these results suggest that E6AP expression contributes, in part, to PML degradation and to the loss of PML in B cell lymphoma." (PMID 23734343, 2013). "In our recent study we demonstrated that E6AP elevation is frequently found in human B-cell lymphomas and is associated with PML downregulation." (PMID 23730625, 2013). "Importantly, E6AP levels were elevated and associated with PML downregulation in more than half of the human B-cell lymphomas examined." (PMID 23730625, 2013). "PML involvement in senescence induction has recently gained central stage from studies on human ubiquitin ligase E6AP−/− B-cell lymphomas." (PMID 23847764, 2013). "Inversely, down-regulation of E6AP in B cell lymphoma cells restores PML expression with a concurrent induction of cellular senescence in these cells." (PMID 23734343, 2013). "In addition to HPV-induced cancer, E6AP drives cancer progression in B-cell lymphoma where it degrades PML, allowing the tumor cells to bypass PML-induced senescence." (PMID 31001145, 2019). "In addition, an increase in E6AP expression is correlated with PML down-regulation in human Burkitt’s lymphoma specimens and a number of B cell lymphoma cell lines." (PMID 23734343, 2013). "It becomes apparent that PML is regulated by different molecules in different cancer types, e.g., by E6AP in B-cell lymphoma, CK2, and PIAS1 in NSCL cancer whereas KLHL20/Pin1 in prostate adenocarcinoma." (PMID 23730625, 2013). "Equally, the expression of PML is restored by down-regulation of E6AP in B-lymphoma cells, with concurrent induction of cellular senescence, suggesting that the overriding of PML-induced senescence is essential for B-cell lymphoma progression." (PMID 23847764, 2013). "Indeed, B-cell lymphomas lacking EA6P express elevated level of PML and PML-NBs, with a concomitant increase of markers of senescence." (PMID 23526763, 2013). "Thus, E6AP-mediated PML ubiquitination and degradation potentiates lymphomagenesis by inhibition of cell senescence and elevated E6AP expression likely contributes in part to PML downregulation in B cell lymphomas." (PMID 22935031, 2012). "Furthermore, UBE3A haploinsufficiency in an MYC-driven B-cell lymphomagenesis model increased PML levels, induced cellular senescence, and suppressed tumor progression, which is consistent with elevated levels of UBE3A and decreased levels of PML in primary B-cell lymphoma samples." (PMID 40002221, 2025).
colon carcinoma (8 papers, 2016 to 2025). "PML serves as tumor suppressor and loss, or reduced expression, of PML allows additional tumorigenic mutations to drive the formation of solid tumors, including colon carcinomas." (PMID 38467608, 2024). "Clinical analysis revealed that low expression levels of KLHL39, DAPK, and PML are associated with metastatic progression of human colon cancers." (PMID 27042198, 2016). "Here, the functional consequences of USP22 on PML expression levels were investigated by CRISPR/Cas9-mediated constitutive knock-out (KO) of USP22 in the human HT-29 colon carcinoma cell line, generated." (PMID 38467608, 2024). "Clinically, low expression of KLHL39 in human colon cancer correlates with low expression of PML and DAPK, higher tumor grade, lymph node metastasis, and distant metastasis." (PMID 27200299, 2016). "Similar tumor suppressive functions are observed with KLHL39 in human colon cancer cell lines, and more importantly, these functions are all mediated by a PML- and DAPK-dependent manner." (PMID 27042198, 2016). "Consistent with the clinical observations, KLHL39 suppresses colon cancer migration, invasion, and metastasis, and these tumor-suppressive effects are all mediated through a PML- and DAPK-dependent manner." (PMID 27200299, 2016).
HIV-1 infection (8 papers, 2013 to 2023). The type species of lentivirus and the etiologic agent of acquired immunodeficiency syndrome (AIDS). "In contrast, the modulation of the early stages of HIV-1 infection of human cells by PML has been investigated by RNA interference, with unclear results." (PMID 28656178, 2017). "PML/TRIM19 interferes with HIV-1 infection in human and murine fibroblasts through the reduction of reverse transcriptase products." (PMID 28829373, 2017). "Interest for PML as a modulator of HIV-1 infection surfaced again in recent years, as it was proposed to act as an HIV-1 restriction factor in mouse and human cells." (PMID 28656178, 2017). "We find that the PML-dependent restriction of early-stage HIV-1 infection was increased by treatment with IFN-α or IFN-β, which suggests that PML is relevant to the intrinsic cellular defenses against retroviral infections." (PMID 27000403, 2016). "It has been shown in previous studies that HIV-1 infection triggers an early relocalization of PML bodies from the nucleus to the cytoplasm of infected HeLa cells." (PMID 26703718, 2015). "As As2O3 induces the degradation of PML and dissolves PML-NBs, it has been suggested that PML inhibits HIV-1 infection." (PMID 26703718, 2015). "The role of PML in HIV-1 infection of human cells is controversial." (PMID 28656178, 2017). "Also in support of an indirect effect of PML is the fact that HIV-1 infection of MEFs was inhibited at reverse transcription, a step that takes place in the cytoplasm while PML is predominantly nuclear." (PMID 27000403, 2016). "Second, PML could indirectly interfere with HIV-1 infection and/or transcription by upregulating the production of type I IFN." (PMID 27000403, 2016). "Whether PML/TRIM19 is also active against HIV-1 infection, however, is controversially discussed." (PMID 26703718, 2015). "HIV-1 infection redistributes PML together with the integrase interactor 1 (INI-1) from nucleus to cytoplasm, where PML and IN1-1 colocalize with HIV-1 preintegration complex and interfere with HIV-mediated transduction." (PMID 23761861, 2013). "Here we provide unambiguous, knockout-based evidence that PML does not restrict the early postentry stages of HIV-1 infection in a variety of human cell types and does not participate in the inhibition of HIV-1 by IFN-I." (PMID 28656178, 2017). "However, recent studies have shown that PML knockout did not affect the permissiveness of these cells to HIV-1 infection, indicating that, unlike TRIM5α, PML is not a restrictive factor for HIV-1 in human cell lines." (PMID 38069029, 2023). "Turelli and colleagues reported that PML is transiently exported in the cytoplasm following exposure to HIV-1 and that it colocalizes with the incoming virus in HeLa cells; however, this study did not include functional evidence for the involvement of PML in HIV-1 infection." (PMID 28656178, 2017).
nasopharyngeal carcinoma (7 papers, 2008 to 2025). A carcinoma arising from the nasopharyngeal epithelium. "Here we show that co-administration of GCV and arsenic trioxide (ATO), a PML NB disruptor, reduces tumor volume in a xenograft model of nasopharyngeal carcinoma utilizing CNE1 cells." (PMID 23680002, 2013). "Silencing of USP7 was found to increase the number of PML-NBs, to increase the levels of PML protein and to inhibit PML polyubiquitylation in nasopharyngeal carcinoma cells." (PMID 21305000, 2011). "Additionally, EBV EBNA1 hijacks the host kinase CK2 and the deubiquitinase USP7 to disrupt PML NBs, contributing to nasopharyngeal carcinoma." (PMID 39823515, 2025). "In addition, we recently found that EBNA1 disrupts promyelocytic leukemia (PML) nuclear bodies (also called ND10s) in nasopharyngeal carcinoma cells by inducing the degradation of the PML proteins." (PMID 19834552, 2009). "The EBNA-1-mediated disruption of PML bodies is an important factor for the development of gastric cancer and nasopharyngeal carcinoma (NPC)." (PMID 36830895, 2023). "We further verified this property by examining the effect of BRLF1 on PML nuclear bodies and proteins in CNE2Z nasopharyngeal carcinoma cells." (PMID 29979787, 2018). "In order to investigate the potential role of USP7 in regulating PML-NBs, we treated the EBV-negative nasopharyngeal carcinoma cell line, CNE2, with siRNA for USP7 (siUSP7) or control siRNA for GFP (siGFP)." (PMID 21305000, 2011).
colorectal cancer (6 papers, 2012 to 2025). A primary or metastatic malignant neoplasm that affects the colon or rectum. "Extensive research has demonstrated that PML exhibits significant tumor suppressor functions across various solid tumors such as breast, lung, and colorectal cancers, with overexpression inducing cell cycle arrest, senescence, and programmed cell death." (PMID 41312366, 2025). "Colorectal cancer cells secreted miR-1246 via EVs, which activated Smad1/5/8 signaling through targeting promyelocytic leukemia (PML) mRNA in recipient ECs, promoting angiogenic activities." (PMID 29415727, 2018). "Previous studies have detected that PML interacts with β-catenin in colorectal cancer cells, although little is known about its role in bone." (PMID 25299576, 2014). "In addition to an intrinsic reduction of PML in cancer cells, it was shown that colorectal cancer cells are capable of reducing PML protein abundance in endothelial cells." (PMID 29416846, 2018). "Similarly, microvesicles from colorectal cancer cells contain miR-1246 and TGF-β which are transferred to endothelial cells to silence promyelocytic leukemia protein (PML) and activate Smad 1/5/8 signaling promoting proliferation and migration." (PMID 27231010, 2016).
breast tumors (5 papers, 2016 to 2020). "Consistent with its localization in primary breast tumors and after induced expression, Mad1 localizes to PML NBs in SKBR3 cells." (PMID 30948704, 2019). "The acquisition of aggressiveness and metastatic features in breast tumours is accompanied by the elevated PML expression and enhanced sensitivity to its inhibition." (PMID 27553708, 2016). "PML expression is selectively exacerbated in a subset of breast tumors (TNBC)." (PMID 31570853, 2020). "We observed a strong positive correlation of ERβ-PML with Foxo3a and a negative correlation with Survivin, observed both at protein and mRNA levels, in human breast tumors and normal tissues." (PMID 31506431, 2019).
multiple myeloma (5 papers, 2013 to 2021). "In certain multiple myeloma cells where IFN-α/γ cannot induce PML and PML–NBs, DAPK is persistently ubiquitinated and degraded by KLHL20." (PMID 27200299, 2016). "In support of this notion, in certain multiple myeloma cells where IFN-α/γ fail to induce PML and PML-nuclear bodies, KLHL20 retains in the cytoplasm and perinuclear region, thus allowing a persistent ubiquitination and degradation of DAPK." (PMID 27042198, 2016).
myeloid malignancies (5 papers, 2016 to 2024). "Furthermore, we found that the IDH1/2 point mutations, common in both glial and myeloid malignancies, also disrupt PML-NBs demonstrating that a range of disparate mutations converge on PML." (PMID 38066546, 2023). "Myeloid neoplasms are known to have chromosomal translocations that regulate PML-RARA, CBFB-MYH11, and RUNX1-RUNX1T1 myeloid transcription factors and JAK2, FLT3, KIT, and RAS, activating driver mutations in signaling pathways." (PMID 38392574, 2024).
myocardial infarction (5 papers, 2021 to 2024). Gross necrosis of the myocardium, as a result of interruption of the blood supply to the area, as in coronary thrombosis. "Treatment with arsenic trioxide, which is an ROS inhibitor, reduces RNF4 expression and PML SUMOylation to suppress myocardial apoptosis and fibrosis against myocardial infarction." (PMID 39697538, 2024). "Here, we observed an increase in PML mRNA expression in cardiac fibrotic tissue from mice with myocardial infarction and in TGF-β1-induced cardiac fibroblasts." (PMID 36778116, 2023). "GA can alleviate myocardial infarction-induced cardiac dysfunction and fibrosis through SUMOylation of the PML/Pin1/TGF-β1 pathway." (PMID 35707278, 2022). "Inhibition of SUMO-1 by ginkgoic acid alleviated myocardial infarction-induced heart dysfunction and fibrosis, and the SUMOylated PML/Pin1/TGF-β1 pathway is crucial for ginkgoic acid-inhibited cardiac fibrosis, wherein Pin1 functions as a positive regulator of TGF-β1 mRNA." (PMID 34128158, 2021).
Burkitt lymphoma (4 papers, 2013 to 2022). A rare form of malignant mature B-cell non-Hodgkin lymphoma. "In addition, UBE3A is hyperactivated in Epstein-Barr virus-associated Burkitt’s lymphoma and is involved in degrading the tumor repressor promyelocytic leukemia protein (PML)." (PMID 35368029, 2022). "Approximately 60% of Burkitt’s lymphomas show downregulation of PML expression correlated with high levels of E6AP." (PMID 32751183, 2020). "Hemizygous disruption of the Ube3a gene can attenuate murine B-cell lymphomagenesis driven by the Eμ (immunoglobulin enhancer)-Myc transgene with concomitant upregulation of PML, recapitulating the oncogenic role of E6AP in Burkitt’s lymphoma." (PMID 32751183, 2020). "Considering that LMP1 can increase HLA class I in Burkitt lymphoma, we propose that this LMP1-mediated increase of HLA class I expression might be induced via induction of the number of PML-NBs." (PMID 24009715, 2013).
Disseminated intravascular coagulation (4 papers, 2014 to 2025). Disseminated intravascular coagulation is characterized by the widespread activation of coagulation, which results in the intravascular formation of fibrin and ultimately thrombotic occlusion of small and midsize vessels. "It was noted that the WHO (2017) AML-NOS subcategory closely matched the FAB (1976) AML with maturation (FAB M2) subcategory.The presence of APL with PML-RARA, with concomitant disseminated intravascular coagulation (DIC) and CNS involvement, typically led to a very poor prognosis." (PMID 33973643, 2021).
embryonic carcinoma (4 papers, 2015 to 2017). "This was important since the embryonal carcinoma cell line NT2, which has been used by a number of laboratories to study latency possesses abnormal ND10 structures resulting from lower expression of the structure defining protein PML and the complete loss of Sp100." (PMID 26057166, 2015). "In embryonic carcinoma‏ cells, PML-NBs were shown to be involved in OCT4‏ expression and high level of PML expression was‏ expected in NT2 cells." (PMID 28959333, 2016).
laminopathies (4 papers, 2013 to 2024). "PML cytoplasmic particles (PML-CPs) is found in the laminopathy cells and the number of these particles increases with disease severity." (PMID 23761861, 2013). "Its interaction with lamin A/C and co-localization with promyelocytic leukemia (PML) bodies suggest a vital role in cellular organization and differentiation, hinting at its contribution to the mesenchymal phenotypes observed in laminopathies." (PMID 38994962, 2024). "Further research is needed to identify the origin of PML in the PML-CPs and to investigate whether PML-CPs have direct effect to promote laminopathies." (PMID 23761861, 2013). "The PML-CPs may come from the PML-NBs redistribution, since laminopathies could lead to nuclear rupture." (PMID 23761861, 2013). "One possible explanation for the reduced PML grafting in LMNB1ko cells could be the translocation to the cytoplasm and gradual dissolution of PML bodies during NER, as observed in laminopathy patient fibroblasts." (PMID 38485766, 2024). "Although the biological functions of these peri-nuclear PML aggregates have not been elucidated, the aggregates can be used as markers of laminopathies." (PMID 35594310, 2022). "However, in the laminopathy cells without overt abnormal nucleus, the number of PML-CPs are also significantly increased, suggesting that PML-CPs may also from in the cytoplasm." (PMID 23761861, 2013).
myelodysplastic syndrome (4 papers, 2011 to 2025). A clonal hematopoietic disorder characterized by dysplasia and ineffective hematopoiesis in one or more of the hematopoietic cell lines. "Deregulated Wnt signalling contributes to the development of several AML subtypes including normal karyotype, FLT3-mutant, del(5q)+, myelodysplastic syndrome (MDS)-related, CBF-mutated, and PML-RARα+." (PMID 40301545, 2025). "In this case, we speculated the PML-RARA translocation is an original pathogenesis and thereafter additional cytogenetic abnormalities (del(5q) and -6) common in myelodysplastic syndrome." (PMID 27708545, 2016).
neuroblastoma (4 papers, 2014 to 2024). Neuroblastoma (NB) is the most common solid, extracranial childhood tumor. "As the last example, we have calculated the number, diameter, and volume of PML bodies in mouse neuroblastoma cell lines." (PMID 33596823, 2021). "This SUMOylation drives PML degradation by RNF4-dependent ubiquitination in the neuroblastoma N2a cell line of mice; an in vivo study should be the next step to investigate whether ZNF451-1 could become a potential target for neuroblastoma." (PMID 35408996, 2022).